TRAF1 (TNF receptor associated factor 1)
Diseases named in the same sentence as TRAF1 in open-access papers (continued):
Sharing a sentence is not in itself a finding about the gene and the disease.
ischaemic stroke (2 papers, 2013 to 2019). "Together with our previous results, these findings demonstrate that TRAF1 targets the ASK1/JNK pro-death pathway and the Akt pro-survival pathway, which in turn induces Fas/FasL-associated neuronal apoptosis in ischaemic stroke." (PMID 24284943, 2013). "Therefore, TRAF1 represents a promising and durable therapeutic target for treating ischaemic stroke." (PMID 24284943, 2013). "Moreover, TRAF1-mediated neuronal death was completely abrogated when Fas–Fc and anti-FasL antibodies were employed, suggesting that the Fas/FasL pathway is a major TRAF1 target during ischaemic stroke." (PMID 24284943, 2013).
leukemia (2 papers, 2019 to 2022). A malignant (clonal) hematologic disorder, involving hematopoietic stem cells and characterized by the presence of primitive or atypical myeloid or lymphoid cells in the bone marrow and the blood. "After 6 hours of stimulation with IL-33, we observed significantly increased expression of Bcl-xl, TRAF-1, TRAF-2, and Mcl-1, but not Bcl-2 in leukemia cells." (PMID 30742053, 2019).
liver cancer (2 papers, 2018 to 2025). An epithelial or non-epithelial malignant neoplasm that arises from the liver. "For example, in liver cancer, overexpression of retinoic acid-inducible gene I (RIG-I) can promote M2 polarization of peritoneal macrophages in mice through the RIG-I/MAVS/TRAF1/NF-κB pathway, thus inducing apoptosis of liver cancer cells." (PMID 40131539, 2025).
Liver Fibrosis (2 papers, 2024). "TNFRSF9 regulates T‐cell depletion and apoptosis through activation of the 4‐1BB/TRAF1 pathway, which may be implicated in the pathogenesis of liver fibrosis as well as NAFLD." (PMID 39720899, 2024). "The results indicate that in mice with liver fibrosis, Atg16l1ΔMφ mice exhibit higher expression levels of TRAF1 and NF-κB p65 in their macrophages compared to the Atg16l1FL/FL mice." (PMID 39629085, 2024).
multiple myeloma (2 papers, 2022). "Mechanistic studies showed that ALKBH5 exerted tumorigenic effects in myeloma in an m6A-dependent manner, and TNF receptor-associated factor 1 (TRAF1) was a critical target of ALKBH5." (PMID 34759347, 2022).
nasopharyngeal carcinoma (2 papers, 2015 to 2023). A carcinoma arising from the nasopharyngeal epithelium. "PRDX1 has been shown to repress nasopharyngeal carcinoma cell proliferation, migration, invasion, and epithelial-mesenchymal transition in vitro by inactivating the PI3K/AKT/TRAF1 pathway." (PMID 37227568, 2023). "Similarly, LMP1 highly upregulates TRAF1 expression in transfected keratinocytes, and TRAF1 expression was detectable in 17 of 42 EBV+ undifferentiated nasopharyngeal carcinomas (NPC)." (PMID 25996949, 2015).
non-Hodgkin lymphoma (2 papers, 2018 to 2024). Distinct from Hodgkin lymphoma both morphologically and biologically, non-Hodgkin lymphoma (NHL) is characterized by the absence of Reed-Sternberg cells, can occur at any age, and usually presents as a localized or generalized lymphadenopathy associated with fever and weight loss. "TRAF1 is overexpressed in many B cell related cancers and single nucleotide polymorphisms (SNPs) in TRAF1 have been linked to non-Hodgkin's lymphoma." (PMID 30619326, 2018).
pneumonia (2 papers, 2021 to 2025). An acute, acute and chronic, or chronic inflammation focally or diffusely affecting the lung parenchyma, caused by an infection in one or both of the lungs (by bacteria, viruses, fungi, or mycoplasma.). "Studies have shown that miR-127-5p alleviates severe pneumonia by targeting TRAF1 to inactivate the Akt and NF-κB signaling pathways." (PMID 34749775, 2021). "Without exploring these interactions, the true contribution of TRAF1 to pneumonia severity might be overestimated or underestimated." (PMID 40121492, 2025).
primary biliary cholangitis (2 papers, 2012 to 2013). Primary biliary cholangitis (PBC) is a chronic and slowly progressive cholestatic liver disease of autoimmune etiology characterized by injury of the intrahepatic bile ducts that may eventually lead to liver failure. "Whether TRAF1 polymorphisms confer increased risk for primary biliary cirrhosis (PBC), an autoimmune liver disease which can co-exist with RA, is unknown.Aim of the Study." (PMID 23125866, 2012).
skin tumor (2 papers, 2018 to 2021). "TRAF1−/− mice exhibit increased skin sensitivity to TNFα-induced necrosis and reduced skin tumor formation induced by DMBA/chronic solar UV radiation (UVR)." (PMID 30294322, 2018). "TRAF1 is necessary for the development of UV radiation-induced skin cancer, and the deletion of TRAF1 in mice has been shown to significantly inhibit the formation of skin tumor." (PMID 34749775, 2021).
Stroke (2 papers, 2013 to 2020). Sudden impairment of blood flow to a part of the brain due to occlusion or rupture of an artery to the brain. "Surprisingly, TRAF1 transgenic (TG-TRAF1) mice showed enlarged stroke lesions while TRAF1-deficient (TRAF1-KO) mice showed significant lesion reduction." (PMID 33224951, 2020). "Here we report that tumour necrosis factor receptor-associated factor 1 (TRAF1) expression is markedly induced in wild-type mice 6 h after stroke onset." (PMID 24284943, 2013). "In this study, the authors show that TRAF1 is expressed in mice soon after they have suffered a stroke and that increased TRAF1 expression increases susceptibility to ischaemia-induced apoptosis and brain injury." (PMID 24284943, 2013). "Thus, TRAF1 may underlie, at least in part, post-stroke neuroapoptosis through the ASK1/JNK pathway." (PMID 24284943, 2013). "To elucidate the direct effects of upregulated neuronal TRAF1 expression on stroke outcome, we generated several lines of neuron-specific Traf1 transgenic (TG-TRAF1) mice." (PMID 24284943, 2013). "In the present study, we observed a robust induction of TRAF1 expression in mouse brain neurons 6 h after a stroke." (PMID 24284943, 2013). "Thus, TRAF1 has a critical role in neuronal cell fate in response to I/R, offering a novel therapeutic target for stroke treatment with a relatively longer timeframe of use." (PMID 24284943, 2013). "Consequently, we are cautiously optimistic that TRAF1-mediated activation of the ASK1 pro-death signalling pathway is a promising therapeutic target for stroke management, likely beyond the accessible window of opportunity for tPA therapy." (PMID 24284943, 2013). "First, neuronal TRAF1 was robustly induced during the subacute phase of stroke." (PMID 24284943, 2013). "We hypothesized that if TRAF1 has a detrimental role during stroke, then inhibiting the post-stroke generation of TRAF1 in Traf1 knockout mice (TRAF1-KO) might prevent neuronal damage." (PMID 24284943, 2013). "Our data support a pro-apoptotic role for TRAF1 within a period of hours to days post-stroke." (PMID 24284943, 2013). "Targeting the TRAF1/ASK1 pathway may provide feasible therapies for stroke long after onset." (PMID 24284943, 2013). "However, whether the TRAF1/ASK1 pathway interferes with Akt-mediated neuronal survival during stroke remains to be determined." (PMID 24284943, 2013). "We did not observe gross anatomical differences that might affect stroke outcome, so to eliminate the possibility that TRAF1 might have altered cerebral perfusion and impacted infarct volumes, regional cerebral blood flow (rCBF) was monitored by Doppler flowmetry throughout the MCAO procedure." (PMID 24284943, 2013).
Alzheimer disease (1 paper, 2022). A progressive, neurodegenerative disease characterized by loss of function and death of nerve cells in several areas of the brain leading to loss of cognitive function such as memory and language. "By means of this pipeline, a list of 32 prioritized Alzheimer’s disease (AD) genes were produced and two AD susceptibility genes including PSEN1 and TRAF1 were correctly identified." (PMID 36081461, 2022).
atrophic gastritis (1 paper, 2015). "In the present study, we investigated TRAF1, 4-1BB, and Bcl-xL expression in gastric mucosa derived from H. pylori–infected patients with chronic nonatrophic gastritis (CG), atrophic gastritis (AG), intestinal metaplasia with atypical hyperplasia (IM), and gastric carcinoma (Ca)." (PMID 25737718, 2015).
autoimmune thyroiditis (1 paper, 2010). "Of the confirmed non-HLA RA susceptibility loci, only the CD40 and TRAF1/C5 variants have not been reported to be associated with either CeD or T1D although CD40 is associated with autoimmune thyroiditis." (PMID 20854658, 2010).
Candida infection (1 paper, 2025). "CXCL1 is also mediated for host defense against C. albicans infection, with a previous study showing increased CXCL1 expression in TRAF1-deficient mice, leading to neutrophil recruitment and resulting in Candida infection reduction." (PMID 41294483, 2025).
central nervous system lymphomas (1 paper, 2024). "The expression of TRAF1 is low in renal carcinoma cells and primary central nervous system lymphomas." (PMID 38363947, 2024).
cervical cancer (1 paper, 2017). A primary or metastatic malignant neoplasm involving the cervix. "The present study suggests that TXNDC5 is a susceptibility gene in cervical cancer, and high expression of this gene contributes to abnormal angiogenesis, vasculogenic mimicry and metastasis by down-regulating SERPINF1 and TRAF1 expression." (PMID 29207620, 2017).
cervical tumor (1 paper, 2017). "TXNDC5 contributes to the process of vasculogenic mimicry, cell migration and cell proliferation of cervical tumors by down-regulating SERPINF1 and TRAF1 expression." (PMID 29207620, 2017).
chronic fatigue syndrome (1 paper, 2013). "Finally, work on animal models of chronic fatigue syndrome has also underlined the important pathogenic role of TRAF1-related cytokines, such as TNFα." (PMID 23710202, 2013).
co-infection (1 paper, 2013). "When cells were exposed to OGD, however, co-infection with DN-ASK1 counteracted Ad-TRAF1-induced neuronal cell death and reduced LDH release." (PMID 24284943, 2013).
Cognitive impairment (1 paper, 2024). Abnormal cognition is characterized by deficits in thinking, reasoning, or remembering. "BBCT significantly improved cognitive impairment in a BCAS mouse model by inhibiting microglial and astrocyte activation and regulating the expression of CDC20, EGF, TRAF1, and key proteins in the neuroactive ligand-receptor interaction and neuropeptide signaling pathways." (PMID 38464836, 2024).
COVID-19 (1 paper, 2021). A disease caused by infection with severe acute respiratory syndrome coronavirus 2. "We observed that the pulmonary environment of mild COVID-19 patients induced the upregulation of only five pro-inflammatory genes in MSCs, which code for the chemokines CCL5 and XCL2, plus TRAF1, which has already been identified as an important inflammatory mediator in the lungs." (PMID 35095855, 2021).
Fanconi anemia (1 paper, 2012). Fanconi anemia (FA) is a hereditary DNA repair disorder characterized by progressive pancytopenia with bone marrow failure, variable congenital malformations and predisposition to develop hematological or solid tumors. "In RNA-seq data, TNF receptor-associated factor 1 (TRAF1) was upregulated by 7.96 fold; CUGBP, Elav-like family member 1 (CELF1) was down-regulated by 1.16 fold; and Fanconi anemia, complementation group D2 (FANCD2) was down-regulated by 1.70 fold." (PMID 22359579, 2012).
fungal infection (1 paper, 2020). "TRAF1-deficient mice can better control fungal infection in the skin, a process attributable to the CXCL-neutrophil axis." (PMID 32093731, 2020). "As TRAF1-deficiency was able to boost CXCL1 production in both macrophages and keratinocytes, we next generated bone marrow chimeric mice to address the cell type-specific role for TRAF1 in fungal infection." (PMID 32093731, 2020). "Collectively, our study identifies a critical role for TRAF1 in fungal infection and offers new insights into the host defense mechanisms in containing C. albicans intradermal infection." (PMID 32093731, 2020). "Although TRAF1 is well-known for its role in the regulation of B cell and T cell functions, we found that Rag1−/−Traf1−/− mice were still able to mount a better immune defense against fungal infection than Rag1−/− mice." (PMID 32093731, 2020). "Hence, our work uncovers the complex interaction between immune cells and non-immune cells is imperative of a concerted and effective defense against fungal infection, and TRAF1 has a central role in coordinating this process." (PMID 32093731, 2020). "However, the role of TRAF1 in infection, especially fungal infection, remains elusive." (PMID 32093731, 2020).
gastric disease (1 paper, 2015). "We also determined the association between H. pylori virulence factors (cagA, vacAs1, vacAm1) and TRAF1/4-1BB/Bcl-xL expression at the different stages of gastric disease." (PMID 25737718, 2015). "TRAF1 expression in human gastric mucosa is related to the H. pylori virulence genotype cagA+/vacAs1+/vacAm1+, whereas the correlation of 4-1BB and Bcl-xL gene expression with cagA, vacAs1, and vacAm1 toxicity at different stages of gastric disease have not been studied." (PMID 25737718, 2015).
hepatitis C virus infection (1 paper, 2024). A viral infection caused by the hepatitis C virus. "TRAF1 expression is positively correlated with the expression levels of IL-7R, myeloid cell leukemia-1, and CD107a and is involved in supporting specific CD8+ T cell responses during hepatitis C virus infection." (PMID 38995016, 2024).
HIV-1 infection (1 paper, 2020). The type species of lentivirus and the etiologic agent of acquired immunodeficiency syndrome (AIDS). "Furthermore, consistent with this finding, our RNA-seq data showed that TRAF1 was significantly downregulated after HIV-1 infection, suggesting a correlation between gene expression and promoter methylation." (PMID 33013899, 2020).
hydatid disease (1 paper, 2024). "Key regulatory miRNAs and HUB genes, including miR-9-5p, miR-124, miR-23a-3p, Traf1, and Tnf, emerge as potential therapeutic targets for modulating immune responses and osteogenic processes in hydatid disease, offering new avenues for therapeutic interventions against this parasitic infection." (PMID 38601938, 2024).
ischemia (1 paper, 2020). A hypoperfusion of the BLOOD through an organ or tissue caused by a PATHOLOGIC CONSTRICTION or obstruction of its BLOOD VESSELS, or an absence of BLOOD CIRCULATION. "Furthermore, it may be the N-terminal region or kinase domain of ASK1, rather than the C-terminal region, that is capable of interacting with TRAF1, and that the TRAF domain is essential for TRAF1-induced neuronal injury after ischemia." (PMID 33224951, 2020).
lymph node metastasis (1 paper, 2022). "High expression of TRAF1 in UCBs was positively associated with lymph node metastasis, tumor volume, and tumor recurrence (p < 0.05), and a poor prognosis in UCB patients (p < 0.05)." (PMID 35194031, 2022).
lymphoproliferative disorders (1 paper, 2015). "TRAF1 is amongst the most highly TES1-induced target genes and is abundantly expressed in EBV-associated lymphoproliferative disorders." (PMID 25996949, 2015). "While TRAF1-independent HOIP roles may also have contributed to this phenotype, it nonetheless suggests an important role for M1-pUb chains in LCL growth and survival, and highlights LUBAC as a potential therapeutic target in EBV-associated lymphoproliferative disorders." (PMID 25996949, 2015).
medulloblastoma (1 paper, 2021). A malignant, invasive embryonal neoplasm arising from the cerebellum. "PELP1 knockdown in medulloblastoma cells results in downregulation of NF-κB, including TRAF1 and IL-8, and expression of ECM-related genes MMP7, MMP9, and MMP1465, the latter of which is upregulated by microglia in late-stage NDD development." (PMID 34772945, 2021).
metastatic cancer (1 paper, 2011). A carcinoma which has spread from the original site of growth to another anatomic site. "Increased IL-1α expression correlated with the expression of prometastatic (IL-6 and IL-8) and anti-apoptotic genes (TRAF-1 and cIAP-2) and is associated with invasive and metastatic cancer leading to poor prognosis." (PMID 21139583, 2011).
non-alcoholic fatty liver disease (1 paper, 2021). "In addition, the progress of non-alcoholic fatty liver disease (NAFLD) depends on the regulation of the ASK1/p38/JNK signaling by TRAF1." (PMID 34948191, 2021).
oral epithelial dysplasia (1 paper, 2017). "Expression of TNF receptor-associated factor 1 has been found to be higher in OCSCC than normal oral mucosa and oral epithelial dysplasia, and is associated with reduced overall survival, Moloney murine leukemia virus integration site 1, Lin28 homolog B, and most importantly ALDH1 in OSCC." (PMID 28626726, 2017).
osteoarthritis (1 paper, 2020). A noninflammatory degenerative joint disease occurring chiefly in older persons, characterized by degeneration of the articular cartilage, hypertrophy of bone at the margins and changes in the synovial membrane. "Both TRAF1 and TNFAIP3 were previously identified as osteoarthritis-associated markers." (PMID 32674293, 2020).
pancreatic cancer (1 paper, 2024). "The result of human protein atlas (HPA) database showed the expression of TRAF1 and TYK2 were low in pancreatic cancer, the expression of MET was high." (PMID 38363947, 2024).
peripheral T-cell lymphoma (1 paper, 2024). "The TNF receptor superfamily member 1B (TNFRSF1B), TNFRSF1A linked by the death domain TRADD, and TRAF1 associated with TNF receptors are inhibited in peripheral T-cell lymphoma when chemotherapy resistance occurs." (PMID 38468267, 2024).
plasma cell tumors (1 paper, 2012). "However, constitutive overexpression of TRAF1 in lymphocytes is not tumorigenic in mice suggesting that additional target genes must be critical for the development of plasma cell tumors in p80HT mice." (PMID 22642622, 2012).
respiratory infection (1 paper, 2025). "The findings suggest that modulating the activity of TRAF1, USP7, and SP1 could provide a novel approach for managing this common and potentially severe respiratory infection in infants." (PMID 40121492, 2025).
skin infection (1 paper, 2020). An inflammatory process affecting the skin, caused by bacteria, viruses, parasites, or fungi. "TRAF1-deficient macrophages played a critical role in containing the C. albicans skin infection in vivo." (PMID 32093731, 2020).
squamous cell carcinoma (1 paper, 2018). A carcinoma arising from squamous epithelial cells. "In human skin, TRAF1 is expressed at higher levels, as measured by histology, in actinic keratosis as well as in squamous cell carcinoma, compared to normal skin." (PMID 30619326, 2018).
T-cell lymphoma (1 paper, 2025). "Crucially, here the diagnosis was redirected towards a T-cell lymphoma via NGS testing, which identified a TRAF1::ALK translocation." (PMID 40161372, 2025).
ulcer (1 paper, 2020). "After C. albicans challenge for 3 days, WT recipients reconstituted with TRAF1-deficient bone marrows had significantly ameliorated ulcer and fungal burden than WT recipients reconstituted with WT bone marrows." (PMID 32093731, 2020). "Rag1−/−Traf1−/− mice had a smaller area of ulcer after infection for 3 and 7 days, compared to Rag1−/− mice, suggesting that TRAF1’s role in the innate immune cells is pivotal for the immune defense against C. albicans intradermal infection." (PMID 32093731, 2020).
uterine corpus endometrial carcinoma (1 paper, 2024). A endometrial carcinoma (disease) that involves the body of uterus. "Conversely, reduced TRAF1 expression was observed in Bladder urothelial carcinoma (BLCA), Kidney chromophobe (KICH), and Uterine corpus Endometrial carcinoma (UCEC)." (PMID 38825674, 2024).